Y_RNA (Y RNA )
Gene: Miscellaneous RNA gene on chromosome 6 (108,060,818 to 108,060,930, forward strand). Ensembl gene ENSG00000238490.
Homologues: Orthologues: chimpanzee Y_RNA (100% identical), macaque Y_RNA (96% identical). Paralogues in human: RNY1 (91% identical), Y_RNA (89% identical), Y_RNA (88% identical), RNY1P11 (88% identical), Y_RNA (87% identical), Y_RNA (86% identical), RNY1P7 (85% identical), RNY1P8 (85% identical), Y_RNA (85% identical), Y_RNA (84% identical), Y_RNA (83% identical), Y_RNA (82% identical), and 97 more.